CCR6 (C-C motif chemokine receptor 6)
Diseases named in the same sentence as CCR6 in open-access papers (continued):
Sharing a sentence is not in itself a finding about the gene and the disease.
tumor (continued). "Although CCL20, a ligand of CCR6, was detectable in breast cell culture and frozen breast cancer tissue, it was not detectable in any paraffin embedded tumor samples in this series." (PMID 21624121, 2011). "However, we observed that, in HCC patients, circulating Tregs highly express CCR6 and migrate to CCL20 present in the tumor microenvironment." (PMID 21935436, 2011). "And the proliferation of tumor infiltrating CCR6+Tregs was higher than that in DLNs and PBMCs (data not shown)." (PMID 21655250, 2011). "In all, this research represents as the first report to elucidate the mechanism of the selective enrichment of CCR6+Tregs but not CCR6−Tregs in tumor mass." (PMID 21655250, 2011). "As observed for CCR6 in some cases, weak expression for CCR7 could be observed by tumour cells and tubulus cells of normal kidney tissues as well." (PMID 20969772, 2010). "Whereas the ligand for CCR6, CCL20, was expressed in 34 out of 52 tumor samples (65.4%)." (PMID 19340288, 2009). "Interestingly, CCR6 and CXCR3-Th17/Treg cells secreting IL-17 have been described in colorectal and esophageal cancer, while the presence of IL-17-producing-FoxP3+ cells is related with poor prognosis because they have been shown to promote tumor progression." (PMID 40963621, 2025). "Employing an anti‐CCL20 neutralizing antibody and Foxp3DTR mice, it is demonstrated that CCR6+Foxp3+ regulatory T cells (Tregs) recruited by Gal1‐induced TAMs contributed to reduced infiltration and dysfunctional state of CD8+ T cells, subsequently facilitating tumor progression." (PMID 39853961, 2025). "Notably, in tumor models, Th9 cells aid in promoting cytotoxic CD8+ T cells expansion and activation, through CCL20/CCR6-dependent recruitment of type 1 dendritic cells (DC1), specialized for the cross-presentation of antigen by MHC class I molecules to CD8+T cells." (PMID 39104410, 2024). "The studies showed that this chemokine stimulates the migration of immune cells, that possess CCR6, such as B cells, T cells (particularly Th17 cells and Treg cells), natural killer T (NKT) cells, neutrophils and immature dendritic cells (DC) to the tumor site, which suppress its development." (PMID 37316552, 2023). "Similarly, CCR6, a chemokine receptor selectively expressed in Th17 cells and Tregs, can mediate the migration of circulating Tregs to the TME through the CCL20-CCR6 axis, leading to tumour progression and poor prognosis." (PMID 38259489, 2023). "Importantly though, the tumor-promoting effects of CCR6 signaling appear to rely on CCR6+ stromal cells but not CCR6+ immune cells." (PMID 34771532, 2021). "Moreover, experiments with bone marrow chimeras indicate that tumour-promoting effects of CCR6 signalling are dependent on CCR6+ stromal but not on CCR6+ immune cells." (PMID 32601464, 2020). "Through analysis of paired tumor and non-tumor liver samples from HCC patients, an immunosuppressive gradient has been described with increased expression of chemokine networks such as CXCR3/CXCL10 and CCR6/CCL20 which enhances macrophage and Treg recruitment to the liver." (PMID 31627733, 2019). "They found that CCL20 secreted by tumor cells strongly influences the frequencies of immune-suppressive regulatory Treg cells and TH17 populations, thereby supporting the fact that inhibition of the CCR6/CCL20 duo presents a novel therapeutic strategy in cancer treatment." (PMID 30453514, 2018). "Whereas CCR6 seems to be required for retention of LCH-cells in the various tissues, our in vitro experiments support a role for CXCR4 in the distribution of blood-borne CD1a+CD11c+CXCR4+‘LCH-cell like’ myeloid cells in analogy to both immune cells and tumor cells." (PMID 28255525, 2016). "Hence, MAIT cells may persistently express CCR6 and CXCR6 when they migrate into the tumor environment." (PMID 26837580, 2016).
tumor (continued). "We also found that CCR6+ Tregs, but not their CCR6- counterpart, could dominantly enrich in tumor mass and potential inhibited the function of effector T cells in vivo." (PMID 25279261, 2014). "Other immune cells in tumor microenvironment may also promote DC recruitment, such as Th9 cells, which increase DC infiltration of the tumor mediated by CCR6/CCL20 interaction that generates CD8(+) cytotoxic T lymphocyte (CTLs) responses and inhibit tumor growth." (PMID 25110692, 2014). "Thus, the tumor expression of CCR6 plays a critical role in CRC metastasis, upregulated CCR6 predicts poor survival in CRC patients, and targeting CCR6 expression in tumors may be a potential therapeutic strategy for CRC." (PMID 24979261, 2014). "Thus, we propose that once tumor cells express CCR6, their migration and metastasis behavior could be greatly enhanced by stimulating with CCL20 produced by macrophages or other immune cells in the tumor microenvironment." (PMID 24979261, 2014). "In addition, CCR6/CCL20 interaction in endometrial adenocarcinoma, CXCR1/2/CXCL7 interaction in clear cell renal cell carcinoma, CXCR2/CXCL8 interaction in nasopharyngeal carcinoma, and CXCR6/CXCR16 interaction in HCC are reported to promote tumor cell growth." (PMID 25110692, 2014). "Furthermore, we demonstrated that DT treatment did not decrease CCR6 expression by CMT93GFP mouse tumor cells in comparison to DTmu." (PMID 21559338, 2011). "Different from the report that tumor cells could induce the proliferation of Tregs, we couldn't observe any effect of 4T1 tumor cells on the proliferation of CCR6+Tregs in vitro (data not shown)." (PMID 21655250, 2011). "Notably, we extended others work by demonstrating that CCR6+ Tregs, but not CCR6−Tregs, predominantly proliferate in tumor mass." (PMID 21655250, 2011). "It was found that the percentage of CFSE+ CCR6+Treg cells (41.64%) were significantly higher than that of CFSE+ CCR6−Treg cells (14.21%) (p<0.05) indicating that CCR6+Tregs could more powerfully proliferate than CCR6−Tregs in tumor mass." (PMID 21655250, 2011). "In this model, tumor-infiltrating lymphocytes (TIL) will not express CCR6." (PMID 21559338, 2011). "CD1a+ DCs within the tumour area and normal kidney tissue demonstrated co-expression for CCR6, whereas no expression for CCR7 could be observed as determined by immunohistochemistry and double-immunofluorescence studies." (PMID 20969772, 2010). "However, in the presence of increased levels of VEGF, chemoattraction of CCR6+ DC precursors resulted in a dramatic acceleration of tumour growth and reduced survival compared to tumours with no β-defensin expression." (PMID 15785750, 2005). "Notably, chemokine receptors, including C-C chemokine receptor type 2, 4, 5, 6, 8, 10 (CCR2, CCR4, CCR5, CCR6, CCR8, CCR10), and C-X-C chemokine receptor type 3, 4 (CXCR3, CXCR4) have been identified as significant factors in the recruitment of Treg cells to the tumor site." (PMID 39000453, 2024). "Moreover, our present data also showed that tumor-resisent DCs could significantly promote the proliferation of CCR6+Tregs but not CCR6−Tregs." (PMID 21655250, 2011). "Although the tumor microenvironment (TME) is critical in cancer biology, this study did not extensively explore the impact of the CCL20/CCR6 axis on the immune TME." (PMID 40444282, 2025). "The TAMs and lymphocytes had strong communication with the tumour cells in the responders, while in the non-responders, the cytotoxic CD8+ T-cells were in close proximity with immunosuppressive arginase 1 and CCR6 expressing CD163− TAMs." (PMID 38386105, 2024). "CCR4+CCR6+ TAM were found to be significantly reduced after nCIT, while the percentage of total macrophages in the tumor microenvironment was not changed." (PMID 39703499, 2024).
tumor (continued). "The expression of CCR6 is decreased in non-hematopoietic cells present in tumor samples of CRC liver metastasis patients compared to non-tumor samples, but elevated in tumor samples with a desmoplastic growth pattern compared to non-desmoplastic samples." (PMID 37370832, 2023). "Our standard process for dissociation of tumour tissue specimens using gentleMACS reagents was found to significantly diminish CXCR3 and CCR6 staining (data not shown)." (PMID 35464424, 2022). "Lu and colleagues found that the anti-tumor efficacy of Th9 subsets was independent of mast cells but was highly correlated with CCL20, the ligand of CCR6, derived from bronchial and alveolar epithelial cells." (PMID 32508847, 2020). "This helps in regaining activation of naive CD8+ T cells with the homing capacity to the primary tumor and multiple metastatic sites, although other homing receptors are not studied here except CCR5 and CCR6 with showing expression." (PMID 32211313, 2020). "In a large CRC cohort, tumor-infiltrating IL17-producing cells have not worsened clinical outcome and recruit highly cytotoxic CCR5+CCR6+CD8+ T cells via the release of CCL5 and CCL20." (PMID 32707869, 2020). "The expression level of CCR6, but not CD68, was significantly higher in the ≥T2, N+, and N+ samples than in the T1 localized small tumor samples." (PMID 31905918, 2019). "TNF-α induced a significant increase in the percentage of cells expressing CCR6, both in TPC-1 and BCPAP tumor cell lines, but not in normal human thyroid cells." (PMID 29977225, 2018). "In all our cases, lymphocytes intermingled between tumor cells and in tumor stroma were deactivated (negative for activation markers CD25, CD28, CXCR3, CCR6), thus not attacking tumor cells." (PMID 29520483, 2018). "Staining lung tissue indicated CCR6 presence on alveolar epithelial cells II (AEC-II) and fibroblasts in idiopathic pulmonary fibrotic (IPF) lungs that blocks airways, but not in tumor-free areas of squamous cell carcinoma patients." (PMID 30004409, 2018). "Thus, a Ccr6-positive immune system did not significantly affect tumour growth, indicating that the action of CCL20 on angiogenesis is more important during tumour progression than its role in immune cell recruitment in this model." (PMID 32601464, 2020). "To conclude, except for CCR6 and CCR10, CD39+ and CD39− Treg in tumors have a largely similar chemokine receptor expression, and chemokine receptor usage alone can probably not explain the preferred accumulation of CD39+ Treg in the tumor." (PMID 30651930, 2018).
cancer (132 papers, 2009 to 2026). A tumor composed of atypical neoplastic, often pleomorphic cells that invade other tissues. "The intratumoral infiltration of C-C motif chemokine receptor 6 (CCR6)+ cells was associated with favorable prognosis in some human CCL20-producing cancers." (PMID 36726985, 2022). "Our results were consistent with previous researches that CCR6 is associated with EMT in various cancers." (PMID 29383156, 2017). "The pathogenic role of CCL20-induced CCR6 signaling is particularly well established in cancer." (PMID 38472446, 2024). "Notably, the pharmacological inhibition of CCR6 effectively reversed acquired resistance to EGFRi in cancer cells and disrupted resistance-associated glucose metabolism." (PMID 38551001, 2024). "CCR6 has been associated with a wide range of cancer types, such as hepatocellular carcinoma, colorectal cancer, breast cancer, prostate cancer, ovarian cancer, lung cancer, cancer pancreatic, cervical cancer and renal." (PMID 37092451, 2023). "We also retrieved and analyzed Stomach Adenocarcinoma (STAD) RNA-seq data from TCGA cancer database using The Human Protein Atlas’s Kaplan–Meier survival analysis tool and found that CCR6 mRNA expression was negatively associated with GC patient overall survival." (PMID 37572185, 2023). "It has been reported that the expression levels of CCL20 and CCR6 are increased in many cancers such as gliomas, and colorectal and pancreatic cancers, and the increased expression of these molecules is closely associated with poor prognosis in cancer patients." (PMID 26789110, 2016). "Chemokines are essential mediators of immune responses, and the CCL20/CCR6 chemokine signaling axis is known to be involved in inflammation, infectious diseases, and cancer progression." (PMID 40853122, 2025). "CCL20 and its receptor CCR6 are involved in the progression, migration, invasion and angiogenesis of cancer cells, including HCC cells." (PMID 38493218, 2024). "Less is known about the role of CD196/CCR6+ exosomes in traumatic injury, and only a few studies describe such particles in different types of cancer." (PMID 38533491, 2024). "We found that some tertiary lymphoid structure-related genes such as LAT, RBP5, SKAP1, and CCR6 were positively correlated with MHCsig in pan-cancer." (PMID 38714579, 2024). "CCL20, also known as liver activation regulated chemokine (LARC) or macrophage inflammatory protein-3α (MIP-3α), is a pro-inflammatory chemokine that has been involved, together with its receptor CCR6, in cancer metastasis and various autoimmune diseases." (PMID 36835506, 2023). "Accumulating data show that the alteration of CCL20/CCR6 axis promotes cancer progression in various types of tumors including GC." (PMID 37572185, 2023). "Eomesodermin has been shown to be generated by oesophageal adenocarcinoma, and this has been shown to drive CCL20 secretion, which binds to CCR6 on Tregs driving Treg chemotaxis and residency intratumorally, promoting cancer growth." (PMID 38283365, 2023). "CCR6 levels were compared in cancer and non-carcinoma samples in GTEx and TCGA databases; as a result, CCR6 showed significant upregulation within many cancers, such as CM (p < 0.05)." (PMID 37182147, 2023). "In ovarian cancer, increased CCR6 expression in cancer cells has been found to predict poor prognosis." (PMID 36428581, 2022). "For example, in a clinical study about ovarian cancer, the macrophages are activated after cisplatin chemotherapy, which increase CCL20 level and activate CCR6 of cancer cells to trigger EMT and reduce efficacy of chemotherapy." (PMID 35672862, 2022). "M2-like TAMs secrete CCL20 to activate CCR6 in cancer cells to enhance metastasis of primary melanoma." (PMID 35672862, 2022). "Chemokines (CCR1, CCR2, CCR3, CCR4, CCR5, CCR6, CCR7, and CCR8) and receptor genes (CXCL1-17, CCL1-14, CCL16-26) were positively associated with necroptosis levels in various cancers." (PMID 36170029, 2022).
cancer (continued). "The CCL20/CCR6 axis plays a crucial role in the development of cancers and autoimmune diseases by promoting cell proliferation and migration and remodeling the immune microenvironment." (PMID 35841069, 2022). "With concerted, extensive efforts, the functional role played by the CCL20/CCR6 axis is gradually being unfolded, particularly in regulating cancer progression and metastasis within the TME." (PMID 35702353, 2022). "The CCL20/CCR6 axis has been shown to promote cancer progression through pro-angiogenic and immunosuppressive effects as well as through direct stimulation of cancer cell migration and proliferation." (PMID 36107259, 2022). "C-C motif chemokine 20 (CCL20) has been found to have a crucial role in cancer as a mediator by interacting with C-C motif chemokine receptor 6 (CCR6)." (PMID 36439472, 2022). "This ligand has been found to enhance the migration and proliferation of cancer cells through the CCL20/CCR6 signaling pathway and to inhibit cell apoptosis, which directly promotes cancer progression." (PMID 35480896, 2022). "The expression of CCR6 is increased in other cancers, such as liver and colorectal cancer, and has a role in autoimmunity in inflammatory bowel disease." (PMID 36428581, 2022). "CCR6 has a unique ligand CCL20 (MIP-3α) which is expressed in many healthy tissues but also by cancer cells and M2 TAMs." (PMID 36429101, 2022). "The chemokine CCL20 and its receptor CCR6 promotes cancer progression by increasing the proliferation and migration of cancer cells." (PMID 36226048, 2022). "The raised levels of CCR6 promote epithelial-mesenchymal transition of cancer cells, leading to increased cell mobility and metastasis as well as the shedding of cancer cells into the abdominal cavity." (PMID 36428581, 2022). "Although most of them are developed to treat various types of inflammatory diseases, e.g., CCX9664, a small molecule antagonist of CCR6, is being studied in rheumatoid arthritis, they are also potential candidates for the treatment of cancer." (PMID 33919517, 2021). "Apart from the immune-regulatory function, the elevated expression of CCR6 has been previously shown in various cancers, with complicated anti-cancer or pro-cancer potentials." (PMID 35096593, 2021). "Next, we observed significant associations of the expression levels of CD20 with CCR6 (total rho=0.62), CCR7 (total rho=0.79), and CXCR5 (total rho=0.73) in most cancer types." (PMID 35069521, 2021). "Because the macrophage-like cells showed markedly higher expressions of CCR6 compared with SCC25 in in vitro experiments, CCR6 expression in cancer cells was excluded from the immunohistochemical analysis in this study." (PMID 34178651, 2021). "The present article highlighted the unique role of chemokine (C-C motif) ligand 20 (CCL20), which belongs to the CC chemokine family, and its specific receptor C-C chemokine receptor 6 (CCR6) in cancer progression." (PMID 32707869, 2020). "The CCL20/CCR6 network facilitates Treg activity and induces immune suppression to mediate cancer cell elimination and metastasis." (PMID 31991604, 2020). "Apart from NIR1, CCR8 and CCR6 have also been validated as CCL18 receptors in existing cancer research." (PMID 32641093, 2020). "There was a significant difference in CCR6 staining between the cancer and normal areas in the RCC tissues." (PMID 31905918, 2019). "Reference 90 to “Dellacasagrande, J.; Schreurs, O.J.; Hofgaard, P.O.; Omholt, H.; Steinsvoll, S.; Schenck, K.; Bogen, B.; Dembic, Z. Liver metastasis of cancer facilitated by chemokine receptor CCR6." (PMID 31146450, 2019). "The correct reference is “Dellacasagrande, J.; Schreurs, O.J.; Hofgaard, P.O.; Omholt, H.; Steinsvoll, S.; Schenck, K.; Bogen, B.; Dembic, Z. Liver metastasis of cancer facilitated by chemokine receptor CCR6." (PMID 31146450, 2019).